INS (insulin)
Diseases named in the same sentence as INS in open-access papers (continued):
Sharing a sentence is not in itself a finding about the gene and the disease.
Hyperinsulinemia (continued). "In a mice model of reduced hepatic insulin clearance, hyperinsulinemia, which can be seen in some obese children, has been associated with reduced bone turnover and, consequently, poor bone quality." (PMID 40685394, 2025). "Cancer progression and insulin signaling are directly related, where hyperinsulinemia leads to excessive activation of the insulin receptor (IR), which is highly expressed in cancer cells." (PMID 41007744, 2025). "In the liver, adipose tissue, and skeletal muscles, chronic hyperinsulinemia, secondary to persistent hyperglycemia, further diminishes insulin signaling." (PMID 41614828, 2025). "Even high doses of exogenous insulin can down-regulate its own receptor and promote fat formation, worsening IR and requiring higher doses, known as “hyperinsulinemia-induced IR”." (PMID 41463398, 2025). "The fetus’s response to the excess substrates is to produce more insulin, leading to fetal hyperinsulinemia, which can result in a series of consequences, particularly rapid fetal growth." (PMID 40958678, 2025). "Hyperinsulinemia, a compensatory response to insulin resistance, further exacerbates metabolic dysfunction by promoting lipogenesis and impairing lipid metabolism." (PMID 40150467, 2025). "Improved insulin sensitivity helps lower circulating insulin levels, which can reduce hyperinsulinemia-driven androgen production by the ovaries." (PMID 40430499, 2025). "The study aims to assess the three key determinants of hyperinsulinemia: insulin clearance, secretion, and sensitivity in paediatric patients with OSA." (PMID 40365648, 2025). "Serum insulin was further classified into normal range and hyperinsulinemia using a threshold of 10 μU/mL." (PMID 41464556, 2025). "In order to compensate for insulin resistance or insensitivity, the pancreatic beta cells secrete more insulin (hyperinsulinemia) to maintain sugar homeostasis." (PMID 39859066, 2025). "In this study, the detection of hyperinsulinemia in rotenone-treated rats suggests a possible metabolic disruption in the insulin regulation pathway due to rotenone’s effect on the peripheral dopaminergic system." (PMID 39851552, 2025). "Excessive iron accumulation in the liver disrupts glucose metabolism, resulting in hyperinsulinemia, primarily due to reduced insulin extraction and impaired insulin signaling." (PMID 41235057, 2025). "INS, the gene encoding insulin, has also been implicated in the pathogenesis of PDAC, where aberrant insulin signaling and hyperinsulinemia are thought to contribute to the metabolic alterations that support tumor growth and survival." (PMID 40699634, 2025). "Hyperinsulinemia and IR and, observed in this study and previously, impair glucose utilization while also limiting ketone production due to insulin’s anti-lipolytic effect, contributing to cognitive decline." (PMID 40319428, 2025). "During this stage, the insulin secretion index compensatorily increases, resulting in a state of hyperinsulinemia." (PMID 41018201, 2025). "The high content of PA in the membrane of erythrocyte and hepatocytes makes it more rigid, with a decrease in the affinity of insulin to its receptor that results in decreased insulin sensitivity and hyperinsulinemia." (PMID 39859502, 2025). "When IR develops, a compensatory hyperinsulinemia occurs, due to the increased secretion of insulin (extra-insulin) from the pancreatic β-cell to achieve normoglycemia, which leads to an inadequate or vicious cycle of IR ↔ hyperinsulinemia." (PMID 40943177, 2025). "Beyond cellular mechanisms, flavonoids exert systemic effects by improving pancreatic β-cell function and reducing hyperinsulinemia, which in turn lessens the stimulatory effect of insulin on ovarian androgen production." (PMID 41155686, 2025). "A major effect of insulin (hyperinsulinemia) is promoting lipogenesis by stimulating fatty acid uptake and triglyceride synthesis in fat cells." (PMID 41009753, 2025).
Hyperinsulinemia (continued). "In IR, cells exhibit decreased sensitivity to insulin, leading to elevated blood glucose levels and increased insulin production by the pancreas, a condition known as compensatory hyperinsulinemia." (PMID 40009162, 2025). "In contrast, previous studies that induced hyperinsulinemia measured insulin sensitivity and endothelial dysfunction immediately after the intervention." (PMID 40045281, 2025). "Nevertheless, insulin exerts different actions in specific tissues and cells, which are reflected in the variety of physiological and pathological effects of IR and hyperinsulinemia." (PMID 40565766, 2025). "Numerous studies highlight the effect of insulin on renal sodium transport and metabolism; and demonstrate that individuals with arterial hypertension have reduced insulin sensitivity and hyperinsulinemia, compared to subjects with normal blood pressure." (PMID 40248508, 2025). "It reduces the body's ability to effectively utilize insulin, resulting in elevated blood glucose levels and compensatory hyperinsulinemia." (PMID 40694958, 2025). "The chronic elevation in peripheral insulin (peripheral hyperinsulinemia) levels impacts central insulin availability and function." (PMID 40943177, 2025). "Following glucose consumption, the concentration of plasma glucose influences the release of insulin by pancreatic β cells, resulting in hyperinsulinemia." (PMID 40283443, 2025). "It reduces the responsiveness of tissues such as skeletal muscle, liver, and adipose tissue to insulin, leading to compensatory hyperinsulinemia." (PMID 41403736, 2025). "Firstly, pancreatic cancer and IR exhibit contrasting characteristics: pancreatic cancer is often marked by reduced insulin secretion, while the latter manifests as hyperinsulinemia, indicating a more complex mechanism than other tumors." (PMID 40756516, 2025). "As blood glucose is not efficiently transported into cells, the pancreas compensates by secreting more insulin, resulting in hyperinsulinemia." (PMID 41011571, 2025). "Individuals with stress disorders often exhibit hyperinsulinemia emphasizing the potential role of insulin dysregulation in stress-related health impairments." (PMID 39874242, 2025). "Thirdly, physical exercise reduces blood pressure by increasing insulin sensitivity in trained muscles and thereby alleviating hyperinsulinemia." (PMID 41293048, 2025). "Children born SGA show reduced insulin sensitivity along with compensatory hyperinsulinemia to maintain normoglycemia." (PMID 40889096, 2025). "Our future research will determine how a short-term reduction in iatrogenic peripheral hyperinsulinemia improves insulin sensitivity and endothelial function, aiming to uncover novel strategies for mitigating cardiometabolic risk in this population." (PMID 40045281, 2025). "By enhancing PI3K/AKT signaling, GLP-1RAs restore insulin sensitivity, mitigate hyperinsulinemia, and suppress inflammatory pathways (NF-κB, TLR4)." (PMID 41403736, 2025). "The overall weighted median fasting insulin level, prevalence rates of hyperinsulinemia, and IR were 9.9 μU/ml (95% CI: 9.6, 10.1), 17.2% (95% CI: 15.7, 18.6), and 16.4% (95% CI: 15.2, 17.9), respectively." (PMID 40365140, 2025). "This produces increased circulating insulin levels, namely hyperinsulinemia, which is a constant and essential feature of IR." (PMID 41463109, 2025). "The hyperinsulinemia in this study was the consequence of a combined effect of an increased insulin secretion and reduced insulin clearance." (PMID 41009753, 2025). "In murine models, AdipoR2 deficiency leads to hyperinsulinemia, reduced PPAR-α activation, and increased oxidative stress and hepatic inflammation, whereas its overexpression improves glucose homeostasis, insulin sensitivity, and reduces hepatic steatosis." (PMID 41305006, 2025). "It has also been proposed that hyperinsulinemia dysregulates the balance of the insulin-GH-IGF axis, promoting lipid deposition." (PMID 41514592, 2025).
Hyperinsulinemia (continued). "The directionality of relationships between insulin secretion, insulin resistance, and liver fat is complex, with evidence supporting both insulin resistance driving hyperinsulinemia and vice versa." (PMID 40502600, 2025). "Laboratory tests revealed hyperinsulinemia (insulin >600.00 μIU/ml in both patients), a dissociation phenomenon between blood insulin and C-peptide levels, and positive IAAs." (PMID 41234224, 2025). "Possible mechanisms for improved insulin sensitivity were postulated to be improved glycemic control and lower total insulin dose, resulting in reduced systemic hyperinsulinemia." (PMID 39998445, 2025). "In T2D, sustained hyperinsulinemia results in reduced brain ability to transport insulin through the blood-brain barrier (BBB), thereby compromising the brain’s insulin availability and sensitivity." (PMID 41003796, 2025). "Compensatory hyperinsulinemia induces overstimulation of non-insulin-sensitive tissues, including ovary." (PMID 40066975, 2025). "Eight participants underwent five consecutive HBOT sessions, and insulin sensitivity was assessed using the hyperinsulinemia–euglycemic clamp technique." (PMID 41462642, 2025). "Although most AS events occur in coding regions, variations in UTRs also affect translation efficiency, as seen in insulin mRNA, where a 5′UTR variant alters insulin synthesis and secretion, leading to hyperinsulinemia." (PMID 40425033, 2025). "This condition results in elevated blood glucose levels and compensatory hyperinsulinemia as the pancreas seeks to mitigate the decreased insulin sensitivity." (PMID 40002645, 2025). "This means that the body needs to produce more insulin to keep its blood glucose levels in check, leading to elevated insulin levels (hyperinsulinemia)." (PMID 40572675, 2025). "Early-stage pancreatic cancer is characterized by IR and compensatory hyperinsulinemia, whereas advanced pancreatic cancer is characterized by a reduction in IR and insulin secretion to establish a new metabolic equilibrium." (PMID 40756516, 2025). "Pharmacological activation of RXR improves insulin sensitivity and attenuates hyperglycemia, hypertriglyceridemia, hyperinsulinemia, weight gain, and food intake in diabetic and obese mouse models." (PMID 41438090, 2025). "Consistent with the preceding findings, individuals in Pre_IIb exhibit poorer metabolic profiles, marked by advanced age, being overweight or obese, reduced insulin sensitivity, and hyperinsulinemia." (PMID 40191259, 2025). "These metabolic products cross the placenta and enter the fetal circulation, stimulating fetal pancreatic β-cell proliferation and insulin secretion, leading to fetal hyperinsulinemia." (PMID 40797060, 2025). "The rationale of adjuvant treatment in T1D can be basically attributed to the effect of such therapy on supraphysiologic hyperinsulinemia generated by insulin replacement." (PMID 40914967, 2025). "It is possible that in states of hyperinsulinemia, insulin would overpromote further prostatic tissue growth, considering that insulin is a growth-stimulating hormone." (PMID 40984953, 2025). "Insulin concentrations exceeded 24 mU/L (p < 0.0001) in hyperinsulinemia control mares or those with Cushing’s syndrome." (PMID 40901060, 2025). "In response to IR, the pancreatic β-cells orchestrate a compensatory insulin hyper-secretory response, thereby leading to hyperinsulinemia." (PMID 40806650, 2025). "Studies have found that patients with declining cognition exhibited baseline hyperinsulinemia and elevated plasma c-peptide levels with normal c-peptide/insulin ratios, suggesting that insulin production was increased, but insulin clearance was normal." (PMID 39963470, 2025). "Individuals with a missense mutation in the LRP6 gene typically exhibit impaired insulin signaling in skeletal muscle, resulting in hyperinsulinemia, and poor insulin sensitivity." (PMID 40381169, 2025).
Hyperinsulinemia (continued). "Metformin is commonly used to treat PCOS as it successfully improves insulin sensitivity, reduces hyperinsulinemia, and lowers androgen levels." (PMID 40869469, 2025). "Remarkably, leptin administration reverses hyperinsulinemia; even low doses can reduce insulin levels by 41%, with higher doses normalizing levels to those seen in lean mice." (PMID 41226331, 2025). "Decreased insulin levels in the cerebrospinal fluid (CSF) of AD patients, likely due to peripheral hyperinsulinemia and reduced transport across the blood–brain barrier (BBB), further complicate this relationship." (PMID 41444683, 2025). "While insulin regulates glucose and lipid homeostasis, insulin resistance and hyperinsulinemia amplify oxidative stress, contributing to diseases like T2DM and cardiovascular disorders." (PMID 39940939, 2025). "In IR, increased vascular tone stemming counteracts NO/PGI2-mediated vasodilation during hyperinsulinemia by impairment of IRS/PI3K/AKT insulin pathway by JNK." (PMID 40406487, 2025). "A few studies have reported hyperinsulinemia in malaria, however, these were induced by quinine, an anti-malarial drug that stimulates pancreatic beta cells to release insulin." (PMID 40702267, 2025). "Among these, metformin, a biguanide with insulin-sensitizing properties, has been shown to reduce hyperinsulinemia and hyperandrogenemia levels, typical features of PCOS, thereby improving ovulation." (PMID 41411269, 2025). "In this condition, cells require higher levels of insulin to respond appropriately, increasing the secretion of the hormone by the β-cells in the pancreas, leading to hyperinsulinemia despite normal glycemia." (PMID 40871560, 2025). "As a result, the pancreas compensates by increasing insulin secretion, which leads to hyperinsulinemia." (PMID 40959347, 2025). "Hyperinsulinemia is a subtle signal of the genome that indicates successful restoration of estrogen signaling at the expense of excessive insulin synthesis." (PMID 41514592, 2025). "IR, characterized by the diminished sensitivity of insulin-targeting tissues to normal insulin levels, hampers the disposal of insulin-mediated glucose and consequently triggers compensatory hyperinsulinemia." (PMID 40114229, 2025). "In an IR state, the body compensates by secreting more insulin to maintain glucose homeostasis, resulting in hyperinsulinemia." (PMID 40520802, 2025). "Augmented hepatic PTEN and reduced systemic FGF21 levels, in turn, perturbed hepatic as well as systemic insulin sensitivity, leading to basal hyperinsulinemia and impaired glucose tolerance." (PMID 40311678, 2025). "As a result, the pancreatic β-cells augment their insulin secretory capacity to offset the IR resulting in the increase in plasma insulin concentration (hyperinsulinemia) such that glucose tolerance/level remains normal or only slightly impaired." (PMID 41473239, 2025). "In conclusion, NHANES data on nondiabetic/nonprediabetic adolescents revealed substantial increases in fasting insulin and the prevalence of hyperinsulinemia and IR over the last two decades in the US." (PMID 40365140, 2025). "Impaired glucose transporter function reduces skeletal muscle glucose uptake, while glucotoxicity and exogenous hyperinsulinemia further diminish peripheral insulin sensitivity in metabolically uncontrolled T1D." (PMID 41257477, 2025). "Chronic HCD exposure in earlier generations likely impaired insulin sensitivity, triggering compensatory hyperinsulinemia." (PMID 40606827, 2025). "In agreement with our results, obese mares and those with a body condition score (BCS) greater than 7 had both normal insulin levels and hyperinsulinemia." (PMID 40901060, 2025). "Another meta-analysis of eight RCTs reported improvements in hyperinsulinemia, IR, and insulin sensitivity following melatonin supplementation." (PMID 41515249, 2025).
Hyperinsulinemia (continued). "Lastly, the improvement in fasting insulin levels (pooled WMD of −0.62 μU/mL) aligns with prior evidence indicating that bariatric surgery reduces compensatory hyperinsulinemia." (PMID 40626220, 2025). "Conversely, reduced adiponectin levels diminish insulin sensitivity, exacerbating hyperinsulinemia and its downstream effects on androgen production and inflammatory pathways." (PMID 41393278, 2025). "Insufficient insulin function triggers compensatory hyperinsulinemia, necessitating continuous insulin secretion by islet beta cells." (PMID 41048425, 2025). "In comparison to MSG-NO rats, splenectomy in MSG-obese animals can effectively mitigate hyperinsulinemia, enhance insulin sensitivity, and reduce the hypertrophy of adipocytes and islets." (PMID 41377803, 2025). "Concomitant hypoglycaemia, elevated insulin, pro‐insulin, and C‐peptide is indicative of endogenous hyperinsulinism, warranting radiological investigations to identify the tumour source." (PMID 39740208, 2025). "The gold standard for diagnosing hyperinsulinism involves a 72‐h supervised fasting test with measurement of plasma glucose, insulin, C‐peptide, and proinsulin levels." (PMID 40124204, 2025). "Instead, a person with endogenous hyperinsulinism would maintain elevated endogenous insulin secretion, defined in this context as elevated serum concentrations of both insulin and C-peptide." (PMID 40161293, 2025). "Endogenous hyperinsulinism was diagnosed in individuals who had serum glucose <55 mg/dL, serum insulin ≥3.0 μU/mL, and serum C-peptide ≥0.6 ng/mL." (PMID 40161293, 2025). "The results revealed endogenous hyperinsulinemia, with insulin levels of 5.5 μU/mL (reference 2–3 μU/mL) and C-peptide levels of of 2.01 ng/mL (reference: 1.1–1.5 ng/mL)." (PMID 40981133, 2025). "Systemic iatrogenic hyperinsulinism is unavoidable in patients with T1D because insulin is administered subcutaneously instead of being secreted directly into the portal circulation." (PMID 40747135, 2025). "That is, this channel regulates insulin secretion in pancreatic beta cells; therefore, when mutations occur in the genes encoding SUR1 (ABCC8) and Kir6.2 (KCNJ11), serious problems in insulin secretion arise, leading to neonatal diabetes or hyperinsulinism." (PMID 41009376, 2025). "Insulin is the most important fetal growth hormone, and fetal hyperinsulinemia results in excessive fetal growth." (PMID 40235646, 2025). "On the contrary, in women with T1D and PCOS, hyperinsulinism is necessarily related to exogenous insulin, since pancreatic insulin secretion is negligible." (PMID 40747135, 2025). "Diazoxide, which inhibits beta cell insulin release and enhances hepatic glycogenolysis, is used to control hyperinsulinism." (PMID 40697399, 2025). "During the admission, hypoglycemic hyperinsulinism was confirmed (49 mg/dL with non‐suppressed insulin concentrations)." (PMID 41030468, 2025). "Morphometric data of insulin-stained pancreatic specimens from patient 1–5 and a non- congenital hyperinsulinism control." (PMID 41561050, 2025). "A fasting study supported resolution of hyperinsulinism; after a 16-h fast blood glucose was 2.7mmol/L, insulin 1mU/L, β-hydroxybutyrate 1.8mmol/L." (PMID 41084516, 2025). "This condition is likely related to changes in the secretion of gastrointestinal hormones and insulin, with hyperinsulinism produced by incretin release after carbohydrate intake." (PMID 40005017, 2025). "These analyses typically reveal inappropriate insulin levels, often exceeding 10 μIU/mL, as well as detectable C-peptide levels, confirming endogenous hyperinsulinism." (PMID 40904956, 2025). "In PCOS individuals with normal weight or lean body mass, OGTT can accurately identify post-load hyperinsulinemia, late insulin peak, and extended insulin response." (PMID 38337532, 2024). "Hyperinsulinemia and IR promote carcinogenesis via growth promoting and mitogenic effects of insulin and IGF-1." (PMID 39103728, 2024).